IL1B (interleukin 1 beta)
Diseases named in the same sentence as IL1B in open-access papers (continued):
Sharing a sentence is not in itself a finding about the gene and the disease.
asthma (continued). "Taken together our data suggest that caloric restriction should be used for prevention of obese asthma and that IL-1β blockade may be considered as an adjunct therapy." (PMID 30670753, 2019). "Th17-related cytokines such as TNF-α, IL-6, and IL-1β are important in the control of asthma onset." (PMID 31790411, 2019). "For example, studies have demonstrated that ETS exposure results in elevated levels of pro-inflammatory cytokines (e.g., IL-8, IL-1β, TNF-α, IL-1) that may be associated with severe airway inflammation often seen in asthma." (PMID 31766400, 2019). "IL-1β is a key mediator of inflammation, especially in the neutrophilic subtype of asthma." (PMID 31113430, 2019). "The importance of IL-1β in asthma is highlighted by the observations that IL-1β is elevated in BAL fluid and sputum; it is associated with nocturnal asthma; and the expression of its receptor (IL-1R1) is positively correlated to stress markers in asthmatic patients." (PMID 30906226, 2019). "IL-1β could increase bronchial reactivity via up-regulation of TH2/TH17 cells, which were associated with severe asthma phenotype in humans." (PMID 30670753, 2019). "Low grade systemic inflammation observed in the metabolic syndrome may contribute to the development of obese asthma via IL-1β and other pathways." (PMID 29686414, 2018). "There is interest in a role of IL-1β as inducer of IL-17 and IL-6 in asthma." (PMID 29361942, 2018). "We hypothesised that features of asthma exacerbation such as neutrophilic inflammation and Th2-upstream cytokines are dependent on IL-1β signalling." (PMID 29361942, 2018). "Moreover, IL-1β-related signaling pathway also significantlly activated in the lung of asthma and COPD patients." (PMID 29254155, 2017). "There’s studies proved that NLRP3 mediated IL-1β could lead to a vicious cycle between previous and future exacerbations in asthma." (PMID 29311942, 2017). "Further research revealed that NLRP3 inflammasome-mediated IL-1β might be one of the key factors which could induce inflammation and result in asthma, and increasing IL-1β could also be seen as a marker of asthma." (PMID 29311942, 2017). "Pro-inflammatory cytokines, such as TNF-α, IL-1β, and IL-6, are involved in both asthma and COPD and may play a role in amplifying inflammation and thus determining disease severity." (PMID 27812337, 2016). "It has been documented that NLRP3 inflammasome which is responsible for IL-1β maturation may play crucial roles in OVA-induced asthma." (PMID 27793052, 2016). "In a murine model of agricultural (occupational) asthma, repetitive nasal instillation of organic dust extract derived from animal farming operations increased IL-17, IL-1β and IL-6 protein concentrations in lung homogenates as well as induced a neutrophilic infiltrate in the lungs." (PMID 26561853, 2015). "We provide the first evidence of a differential impact of macrolides on the inflammasome/IL-1β axis, which may be of relevance in inflammasome-driven diseases such as chronic obstructive pulmonary disease or asthma." (PMID 26152605, 2015). "The results from our meta-analysis indicate the lack of association between IL-1β -511C/T polymorphism and asthma susceptibility, whereas a significant increased risk existed between asthma and IL-1RA polymorphism." (PMID 25821855, 2015). "The second technique used the IL-1β cutoff point at 130 pg/mL, which was identified as the best classifier to distinguish overlap cluster 2 from clusters 1 or 3 in the test study and was used alongside subject disease status (asthma or COPD)." (PMID 25129678, 2015). "Accumulating evidence also suggests that IL-1β may play an important role in the pathogenesis of asthma." (PMID 25981515, 2015). "The efficacy of anti-IL-1β antibody was previously proven in the treatment of asthmatic guinea pigs, and the present study also supports a therapeutic value for anti-IL-1β antibody in the treatment of refractory asthma." (PMID 25760938, 2015).
asthma (continued). "Compared to healthy control subjects, patients with asthma had significantly more percentages of eosinophils and neutrophils, IL-1RA, IL-1α, IL-1β, IL-2Rα, IL-5, IL-6, IL-7, IL-8, G-CSF, GROα (CXCL1), MIP-1β (CCL4), MIG (CXCL9), RANTES (CCL5) and TRAIL in their BAL fluids." (PMID 26011707, 2015). "IL-1β has a pivotal role in the progression of allergic airway inflammation in asthma." (PMID 25760938, 2015). "Our results indicated that no significant asthma risks of people with IL-1β -511C/T polymorphism are in all subjects." (PMID 25821855, 2015). "Similar IL-1RA levels in asthma inflammatory phenotypes also suggest an impairment of anti-inflammatory responses where increased IL-1RA could oppose the high IL-1β levels." (PMID 25616863, 2015). "However, a recent study showed that mRNA levels of inflammasome components and IL-1β are suppressed in sputum cells obtained from individuals with asthma or allergic rhinitis compared to normal individuals." (PMID 26091108, 2015). "Importantly, ADE genes showed interactions with other asthma-related genes such as IL5 and IL1B which are responsible for the immunological mechanisms of asthma and allergy." (PMID 24895604, 2014). "Moreover, the involvement of inflammasome in an OVA-induced asthma model was shown by the increased generation of IL-1β in broncho-epithelial cells into the lumen of the bronchus." (PMID 24671176, 2014). "In addition, the associations of asthma with the IL5 C-703T polymorphism in Russians from the city of Tomsk and IL1B −511C>T in the Canadian Asthma Primary Prevention Study have been successfully replicated in our study." (PMID 24895604, 2014). "Both IL-1α and IL-1β, for example, are known to be molecules with a strong proinflammatory role, IL-15 has been reported to be elevated in celiac patients in previous studies, and IL-5 plays an important role in the pathophysiology of asthma." (PMID 23533306, 2013). "Although clinical trials of agents that block IL-23 or IL-1β have not been conducted in patients with asthma, future studies are required to elucidate the potential of treatments targeting IL-23 or IL-1β as novel therapeutic strategies for steroid-insensitive asthma." (PMID 24454477, 2013). "The suppression of all the symptoms of asthma in the present study was associated with reduced levels of various Th1 cytokines (TNF-α, IL-6, and IL-1β), with reduced levels of various Th2 cytokines (IL-4, IL-5 and IL13) and with reduced levels of a Th17 cytokines (IL-17F) in splenocytes." (PMID 23346203, 2012). "In addition to understanding how hMSCs regulate in vivo systemic and localized IFNγ/IL-1β levels, our focus will also include factors secreted by the hMSCs or by the host in response to MSCs, which alter the course of asthma." (PMID 20974000, 2010). "IL-1β is a pro-inflammatory cytokine of known importance in asthma pathogenesis." (PMID 16441896, 2006). "In the type 2-low asthma model, Sema3E-deficient mice exhibited increased tissue resistance and elastance, accompanied by elevated levels of neutrophils, dendritic cells, CD4 + T cells, and pro-inflammatory cytokines such as IL-17, TNF, IL-1β, CXCL-8, and MCP-1/CCL2." (PMID 40512736, 2025). "Our data suggest that interventions designed to modulate epithelial responses to Th17 signals, limit viral replication, or dampen synergistic cytokine amplification (e.g., TNF-α or IL-1β blockade) may hold promise for reducing exacerbation severity in non-T2 asthma." (PMID 41332562, 2025). "Emerging evidence suggests that IL-1β may serve as a serum biomarker for identifying severe and persistent cases of allergic rhinitis and asthma and contributes to allergic inflammation by promoting neutrophil recruitment, airway hyperresponsiveness, and mucus secretion." (PMID 41301750, 2025). "Furthermore, exaggerated activation of the NLRP3 inflammasome and production of IL-1β may be correlated with asthma disease severity." (PMID 40343297, 2025).
asthma (continued). "A comparable conclusion regarding IL-1β as a biomarker for atopic diseases was drawn in a study conducted on 3097 children, which demonstrated that IL-1β could serve as a marker for active allergic conditions, including allergic rhinitis, asthma, and atopy." (PMID 39860604, 2025). "In addition, we found that pre-exposure to HDM amplified RV-induced epithelial injury in patients with asthma via enhancement of pro-IL1β expression and release, additional inhibition of type I/III IFNs and activation of auxiliary pro-inflammatory and pro-remodeling proteins." (PMID 37087523, 2023). "Therefore, we hypothesized that excessive RIG-I inflammasome activation and subsequent IL-1β secretion in response to RV infection in asthma, resulted in persistent, but less efficient RIG-I-mediated anti-RV response." (PMID 37087523, 2023). "The three subfamilies of MAPKs have been involved in the pathogenesis of asthma, and JNK and P-38, in particular, are more closely associated with asthmatic airway inflammation, which can cause high expression of downstream factors such as IL-6, IL-1β, and IL-4 and IL-5, respectively." (PMID 36081945, 2022). "However, only IL-1β and IL-2 had the same changing trend between asthma and ACO groups." (PMID 36311545, 2022). "Also, Pro-inflammatory cytokines such as TNF-α, IL-1β, and IL-6 increase in asthma." (PMID 36076196, 2022). "In addition, increased IL-1β and IL-17 also were considered with asthma disease severity." (PMID 35169275, 2022). "This is the first report on the role of BLT1/2 in the regulation of NLRP3 stimulation and IL-1β synthesis in a neutrophilic airway inflammation mouse model, and our results may provide a perspective for the development of treatments for asthma patients with steroid resistance." (PMID 34064821, 2021). "MiR-532-5p could inhibit the IL-1β-induced NF-κB proinflammatory signaling pathway, which suggested that miR-532-5p might be a potential anti-inflammatory mediator attenuating the symptoms of asthma." (PMID 35432797, 2021). "In addition, previous evidence indicates that the activation of NLRP3 inflammasome may lead to increased release of IL-1b and that this increase may be a key factor inducing inflammation and resulting in asthma and may serve as a marker for asthma." (PMID 33645621, 2021). "Therefore, we hypothesized that the maturation of IL-1β in the lungs was dependent on the activation of the NLRP3 inflammasome in HDM-induced asthma." (PMID 34413860, 2021). "Additionally, IL-1β is induced by PAH, and nickel in PM can further enhance mucin secretion, thicken airways, cause inflammation with macrophages and neutrophils, and develop symptoms into respiratory diseases such as COPD and asthma." (PMID 34070821, 2021). "Interestingly, TSLP expression in moDCs from triple co-culture correlated positively with IL12p40, IL-6, and TNF-α in asthma, whereas in COPD with CHI3L1, IL12p40, IL-6, IL-8, TNF-α, and IL-1β suggesting a different pathway of immune response in asthma and COPD." (PMID 32842623, 2020). "Therefore, IL-1β is a potential therapeutic target in asthma." (PMID 32641957, 2019). "Compared with helper T 2 (Th2) cytokines [IL-1β, IL-4, IL-5, and tumor necrosis factor-α (TNF-α)], helper T 1 (Th1) cytokines (IFN-γ and IL-12) are associated to antagonism of immunoglobulin E (IgE) synthesis and Th2 cell responses to restrain the progress of asthma." (PMID 31330806, 2019). "Therefore, new therapeutic approaches for the treatment of allergic diseases, such as asthma and severe rhinitis, could be aided by the development of agents that target the IL-1β." (PMID 31548841, 2019). "Interestingly, we demonstrated significant up-regulation of IL-1β in our asthma exacerbation model." (PMID 29361942, 2018). "Indeed, our data suggest that by targeting IL-1β, both Th2 and neutrophilic components of asthma exacerbations may be reduced." (PMID 29361942, 2018).
asthma (continued). "Hence, to reduce the IL-1β levels and inflammation of local lungs could improve the incidence of asthma and COPD." (PMID 29254155, 2017). "Therefore, targeting elevated IL-1β instead of using corticosteroids might be an effective treatment for asthma." (PMID 29311942, 2017). "Moreover, information on other cytokines such as IL-6 or IL-1β which play an important role in the immunological pathways involved might provide a better understanding of the mechanisms related to asthma due to soybean and DEP." (PMID 28628664, 2017). "In conclusion, this meta-analysis suggests that IL-1β -511C/T polymorphism may not contribute to asthma susceptibility." (PMID 25821855, 2015). "Furthermore, we also found that IL-1β -511C/T polymorphism has no risk of asthma susceptibility when stratified by control source." (PMID 25821855, 2015). "Likewise, NTs are detected in other bronchial smooth muscle cells during asthma or sarcoidosis and their relationship with inflammatory cytokines, IL-1β and interferon (IFN)-γ has been established by the induction of NGF, and BDNF mRNA expression and secretion in cell-culture supernatants." (PMID 25418464, 2014). "In addition, in the obese state, the number of macrophages infiltrating the adipose tissue increases as well as the production of IL-1β, leading to the activation and to the proliferation of IL-17 producing cells and to an increased airway hyperresponsiveness, a key feature of asthma." (PMID 24987694, 2014). "IL-1β is a proinflammatory mediator that is upregulated in respiratory conditions (e.g., cystic fibrosis bronchiectasis, COPD, and asthma)." (PMID 40136649, 2025). "Inflammatory cytokines, such as TNF‐α and IL‐1β, stimulate ASMC proliferation and contribute to the hyperresponsive airway phenotype in asthma." (PMID 40969143, 2025). "In severe asthma, macrophages adopt the M1 phenotype and produce a large amount of pro-inflammatory mediators (including TNF-α, IL-1β, IL-6, NO, etc.)that promote airway mucus secretion, exacerbate lung injury, and accelerate airway remodeling." (PMID 40661956, 2025). "Previous research has shown that the expression of the NLRP3 inflammasome and its downstream product, IL-1β, is increased in the BALF of a mouse model of asthma." (PMID 40343297, 2025). "In patients with severe asthma, pro-inflammatory cytokines in the airway lumen and bronchial mucosa, including TNF-α, IL-1β, IL-6, and IL-8, are mainly produced by macrophages, while LPS can stimulate THP-1 cells to secrete pro-inflammatory cytokines." (PMID 40661956, 2025). "Obese rats with asthma showed significant increases in airway inflammation, pro‐inflammatory cytokine levels, and NLRP3 and IL‐1b mRNA expression." (PMID 40309648, 2025). "These components were subjected to molecular docking studies to evaluate their interaction with key asthma-related targets such as AKT1, TNF, and IL1B." (PMID 40420184, 2025). "Patients with asthma exhibit elevated serum levels of cytokines such as IL6, IL8, TNFα, and IL1β, which activate immune cells including neutrophils, macrophages, and lymphocytes, contributing to the initiation and development of inflammatory responses." (PMID 40598285, 2025). "IL-1β is a proinflammatory mediator that is upregulated in respiratory conditions, such as cystic fibrosis bronchiectasis, COPD, and asthma." (PMID 40136649, 2025). "People with asthma had more NLRP3, ASC, caspase-1, and the pro-inflammatory cytokines IL-1β and IL-18 in their bronchoalveolar lavage fluid and sputum samples." (PMID 41318536, 2025). "In asthma, the NLRP3 inflammasome plays a role in airway inflammation by promoting the release of inflammatory cytokines such as IL-1β." (PMID 40851698, 2025). "Monoclonal antibodies against IL-1β (Canakinumab) and IL-18 (GSK1070806) are in Phase II trials for severe neutrophilic and Th2-low asthma, respectively, providing a direct strategy to quench the inflammatory output of pyroptosis." (PMID 41394843, 2025).
asthma (continued). "Whole-transcriptome sequencing identified key inflammatory genes, such as IL1B, CCL17, and MUC5AC, that were upregulated in asthma patients, while immune regulatory factors like FOXP3 and IFNG were higher in healthy controls." (PMID 40309741, 2025). "Additionally, IL-1β, which is involved in the pathogenesis of asthma, can causes FGF-2 release from chondrocytes, which could promote fibroblast proliferation in the perichondrium and contribute to perichondral fibrosis in asthma." (PMID 41283571, 2025). "This study suggests that IL-1β and iNOS can be biomarkers in the progression of PAR and asthma and decreased lung function, suggesting potential targets for early intervention and treatment." (PMID 38167134, 2024). "Human lung epithelial cells stimulated with IFN-γ, IL-1β, and TNF-α to simulate the inflammatory state present in asthma showed an up-regulation of miR-146a-5p along with an increase in 5-lipoxygenase (5-LO) activity." (PMID 38337625, 2024). "In respiratory diseases like asthma and COPD, NF‐κB, a central inflammatory mediator, can be activated by cytokines such as IL‐1β and TNF‐α." (PMID 39580709, 2024). "In asthma models induced by tobacco extract and PM2.5, inhibiting TRPA1 can reduce the expression of IL-1β and IL-18." (PMID 39735214, 2024). "In this study, we observed an inverse relationship between IL-1β levels and GLCCI1 mRNA levels in sputum from patients with asthma." (PMID 39834584, 2024). "IL-1β, CCL24, and iNOS were significantly higher and E-cadherin was lower in the PAR and asthma group." (PMID 38167134, 2024). "Mice with ovalbumin (OVA)-induced asthma presented with increased pulmonary NLRP3, caspase-1 and IL-1β expression, while the blockage of the NLRP3/caspase-1/IL-1β pathway attenuated bronchial inflammation in asthmatic mice." (PMID 39611173, 2024). "As the interaction between epithelial cells and immune cells is important in asthma, we used A549 cells to investigate the secretion of IL‐1β after TVE treatment in initial experiments, but we were unable to detect any IL‐1β secretion in our conditions." (PMID 38668995, 2024). "Direct targeting of the 3’UTR region of STAT3 by exosome miR-301a-3p reduced the release of inflammatory cytokines TNF-α, IL-1β, and IL-6, which can inhibit OVA-induced asthma." (PMID 39444792, 2024). "Elevated levels of IL-1β, iNOS, and vimentin in the serum were identified as significant indicators of the likelihood of comorbidity of PAR and asthma in children." (PMID 38167134, 2024). "HDM pre-exposure followed by RV infection further increased expression of pro-IL-1β protein, especially in epithelium in asthma, suggesting combined effects of HDM and RV-replication independent and dependent mechanisms on pro-IL-1β expression." (PMID 37087523, 2023). "Clinical observations have especially shown that the proinflammatory cytokines mainly produced by macrophages (e.g., TNF-α, IL-1β, IL-6, and MCP-1) are increased in the BALF of patients with asthma." (PMID 37107297, 2023). "In asthma, Th2 cytokines mediate allergic inflammation, and cytokines such as TNF-α and IL-1β amplify the inflammatory response and play a role in more severe diseases." (PMID 37511021, 2023). "In the present study, there was an increase in the inflammatory markers involved, such as IL-1β, IL-4, IL-5, IL-6, IL-10, IL-13, IL-17, IFN-γ, and TNF-α, in the experimental model of asthma-COPD overlap." (PMID 37511021, 2023). "Inflammatory cytokines, such as TNF-α and IL-1β, increase ASM proliferation and contractile force to restrict airflow in asthma." (PMID 37445635, 2023). "We also demonstrated that mature IL-1β release was paired with formation of ASC specks in HBECs from control individuals and patients with asthma infected with RV." (PMID 37087523, 2023). "Knockdown of RYR2 also inhibited the increase in proinflammatory cytokines, including IL-1β, IL-6, and TNF-α, in rats with asthma and spinal cord injury." (PMID 37422673, 2023).